ZNF226 (zinc finger protein 226)
Description:
May be involved in transcriptional regulation.
Tractability: PROTAC: ubiquitination databases record sites on it.
Gene: Protein-coding gene on chromosome 19 (44,165,073 to 44,178,381, forward strand). Ensembl gene ENSG00000167380.
Subcellular location: Nucleus
Subcellular location (Human Protein Atlas): Nuclear bodies
Pathways (Reactome):
Gene expression (Transcription): Generic Transcription Pathway
Gene Ontology:
Molecular function: transcription cis-regulatory region binding; sequence-specific DNA binding
Biological process: regulation of transcription by RNA polymerase II; negative regulation of transcription by RNA polymerase II; regulation of DNA-templated transcription
Cellular component: nucleus; nucleoplasm
Genetic constraint (gnomAD): Loss-of-function variants: 8 observed, 12.73 expected, observed/expected ratio (o/e) 0.63, 90% interval 0.37 to 1.13. The upper end of that interval is the gene's LOEUF score, 1.13, which puts it in group 4 of 6, group 1 being the genes least tolerant of losing a copy. Missense variants: 1,058 observed, 1,000 expected, observed/expected ratio (o/e) 1.06, 90% interval 1 to 1.11. Synonymous variants: 350 observed, 340.07 expected, observed/expected ratio (o/e) 1.03, 90% interval 0.94 to 1.12.
Homologues: Orthologues: chimpanzee ZNF226 (99% identical), macaque ZNF226 (96% identical), dog ZNF226 (79% identical), guinea pig ZNF226 (73% identical), pig ZNF226 (71% identical), rat Zfp94 (40% identical), mouse Zfp61 (39% identical). Paralogues in human: ZNF234 (66% identical), ZNF112 (45% identical), ZNF229 (40% identical), ZNF45 (40% identical), ZNF227 (39% identical), ZNF235 (38% identical), ZNF33B (37% identical), ZNF28 (36% identical), ZNF658 (36% identical), ZNF224 (36% identical), ZNF726 (36% identical), ZNF254 (35% identical), and 164 more.
Diseases named in the same sentence as ZNF226 in open-access papers:
ZNF226 is named in the same sentence as 2 diseases in open-access papers, as found by Europe PMC text mining. Sharing a sentence is not in itself a finding about the gene and the disease.
ZNF226 shares sentences with these, for which no sentence is quoted: cancer (1 paper); tumor (1).